ENSG00000238685
Synonyms: LOC124900383
Gene: Small nucleolar RNA gene on chromosome 16 (12,297,197 to 12,297,323, reverse strand). Ensembl gene ENSG00000238685.
Gene Ontology:
Biological process: RNA processing
Cellular component: nucleolus
Homologues: Paralogues in human: SNORA78 (82% identical).